CTNNBIP1 (catenin beta interacting protein 1)
Diseases named in the same sentence as CTNNBIP1 in open-access papers (continued):
Sharing a sentence is not in itself a finding about the gene and the disease.
lung carcinoma (continued). "To address this issue, we performed various molecular analyses using lung cancer models that targeted CTNNBIP1, in order to investigate its effect on β-catenin signaling." (PMID 31766223, 2019). "To define the prognostic effects of low CTNNBIP1 in lung cancer patients, we performed a prognosis analysis using this GSE31210 project." (PMID 31766223, 2019). "This is the first study to show that promoter hypermethylation contributes to a decrease in mRNA expression of the CTNNBIP1 gene in lung cancer." (PMID 31766223, 2019). "We analyzed the data from the GSE31210 project, and this showed that a low level of CTNNBIP1 is correlated with stage progression and poorer survival among lung cancer patients." (PMID 31766223, 2019). "CTNNBIP1 was reported as a suppressor in lung cancer that high expression of CTNNBIP1 could inhibit the progression of lung cancer." (PMID 36035315, 2022). "In an effort to better understand how alterations in the CTNNBIP1 status affect nuclear β-catenin accumulation in lung cancer, we carried out a comprehensive molecular analysis of the CTNNBIP1 gene and its relationship with the prognostic data, as well as with β-catenin activity." (PMID 31766223, 2019). "Our findings support the hypothesis that promoter hypermethylation is involved in CTNNBIP1 inactivation among lung cancer patients in Taiwan." (PMID 31766223, 2019). "In addition, the lower level of CTNNBIP1 protein was found in poorly differentiated cases relative to well-differentiated cases, when 90 lung cancer stage IIIa patients were analyzed." (PMID 31766223, 2019). "The search for antagonists or agonists of CTNNBIP1 may also lead to the discovery of new compounds that may potentially be useful when treating lung cancer." (PMID 31766223, 2019). "Next, we examined whether there are any alterations in DNA methylation that affect the CTNNBIP1 gene, using samples from lung cancer patients in Taiwan." (PMID 31766223, 2019). "To examine whether CTNNBIP1 plays a regulatory role in cell motility, we carried out cell adhesion assays, wound healing assays, and transwell-migration assays, using various lung cancer cells that were ectopically expressing CTNNBIP1." (PMID 31766223, 2019). "Our results indicate a significant inverse correlation between the CTNNBIP1 mRNA expression levels and the CTNNBIP1 promoter hypermethylation, which suggests that the promoter hypermethylation is responsible for the low levels of CTNNBIP1 present in many lung cancer patient samples." (PMID 31766223, 2019). "To further confirm the reciprocal relationship between the CTNNBIP1 expression and β-catenin activity in lung cancer, we examined whether the CTNNBIP1 knockdown is able to affect the β-catenin/TCF activity." (PMID 31766223, 2019). "Based on this, we hypothesized that CTNNBIP1 is likely to act as a migration suppressor in lung cancer." (PMID 31766223, 2019). "However, the level of CTNNBIP1 protein was lower in the lung cancer cell lines A549, CL1-0, and CL1-5 compared with the MRC5 cell line." (PMID 31766223, 2019). "To examine whether there were associations between low levels of expression of CTNNBIP1 and the clinical characteristics of lung cancer patients, we analyzed the expression levels of CTNNBIP1 mRNA in a publicly available microarray dataset from the GSE31210 project, namely the PrognoScan database." (PMID 31766223, 2019). "However, little is known about the relationship between CTNNBIP1 and lung cancer." (PMID 31766223, 2019). "However, little is known about the role of CTNNBIP1 in lung cancer." (PMID 31766223, 2019). "All but one (H1299) of these lung cancer cell lines showed promoter hypermethylation, which was in sharp contrast to the situation with the normal lung cell line, MRC5, with in which the CTNNBIP1 promoter was unmethylation." (PMID 31766223, 2019).
lung carcinoma (continued). "Next, we evaluated whether the CTNNBIP1 expression was related to changes in the expression of various β-catenin-targeted genes, such as MMP7, cyclin D1, and c-MYC, among these lung cancer patients." (PMID 31766223, 2019). "Previous studies have indicated that CTNNBIP1 may be a tumor suppressor gene, but its anti-migration properties have not yet been reported for human lung cancers." (PMID 31766223, 2019). "A low expression of CTNNBIP1 is correlated with a high level of expression of MMP7, and there is also an upward trend in terms of the pathological stage and poorer patient survival, which suggests that CTNNBIP1 may be able to serve as a prognostic biomarker for lung cancer." (PMID 31766223, 2019).
psoriasis (2 papers, 2009 to 2012). An autoimmune condition characterized by red, well-delineated plaques with silvery scales that are usually on the extensor surfaces and scalp. "Moreover, we here report down-regulation of two inhibitors of canonical wnt-signalling in psoriasis, ICAT (CTNNBIP1) and WIF." (PMID 19399181, 2009). "Likewise, the downregulation of the canonical wnt inhibitor DKK2, CTNNBIP1 (ICAT), Axin2, as well as FRZB (SFRP3) is common to SCC and psoriasis." (PMID 22384081, 2012).
renal fibrosis (2 papers, 2013 to 2024). A final common manifestation of a wide variety of chronic kidney diseases characterized by glomerulosclerosis and tubulointerstitial fibrosis. "Emerging evidence suggests that altered Wnt/beta-catenin signaling is linked to renal fibrosis pathogenesis Thus, we hypothesized that CTNNBIP1 may be the most statistically significant miR-192/215 target gene." (PMID 23554908, 2013).
cardiac hypertrophy (1 paper, 2019). "MiR-29-induced cardiac hypertrophy appears to be mediated via indirectly activating the Wnt signaling pathway through the repression of four inhibitory factors, namely GSK3B, ICAT/CTNNBIP1, HBP1, and GLIS2." (PMID 31547607, 2019).
colitis (1 paper, 2022). Inflammation of the colon. "Genes related to promoters differentially methylated uniquely in Dnmt3aΔIEC mice (e.g., Cdkn2c, Ccn5, Ctnnbip1, and Sfrp5) at day 5 after the initiation of DSS colitis were enriched in processes related to cell junction and cell proliferation." (PMID 36271073, 2022).
cortical dysplasia (1 paper, 2023). "SFRP1, LRP6, FZD4 and CTNNBIP1 genes showed very similar percentage delta CT values in control tissue and NAAC and with a difference in these delta values in tissue with cortical dysplasia." (PMID 37749503, 2023).
glioblastoma (1 paper, 2019). The most malignant astrocytic tumor (WHO grade IV). "In human glioblastoma, CTNNBIP1 inhibits cell proliferation and invasion, and it induces cell cycle progression arrest and cell apoptosis." (PMID 31766223, 2019). "Likewise, CTNNBIP1 in human glioblastoma cells has been shown to inhibit cell proliferation, reduce cell invasion, bring about cell cycle progression arrest, and cause the induction of cell apoptosis." (PMID 31766223, 2019).
osteosarcoma (1 paper, 2022). A usually aggressive malignant bone-forming mesenchymal neoplasm, predominantly affecting adolescents and young adults. "In research of identifying survival-related genes in osteosarcoma, COL13A1 and CTNNBIP1 were also included as prognostic biomarkers." (PMID 36035315, 2022). "Finally, a 5-gene prognostic model consisting of COL13A1, TNFRSF1A, LILRA6, CTNNBIP1, and CD180 was established for predicting the prognosis of osteosarcoma." (PMID 36035315, 2022).
sarcopenia (1 paper, 2025). Progressive decline in muscle mass due to aging which results in decreased functional capacity of muscles. "KAT2A, CTNNBIP1, GABARAPL1, SEC31A, the expression of IDI1 was highly significantly elevated (p-value < 0.01) in both the Sarcopenia and Control groups in the Sarcopenia dataset GSE8479." (PMID 41325398, 2025).
thyroid cancer (1 paper, 2021). "In thyroid cancer, CTNNBIP1 functions as a negative regulator of the Wnt/β-catenin pathway by decreasing the interaction between β-catenin and TCF/LEF to inhibit the expression of downstream target proteins." (PMID 34162394, 2021). "circRNA_102171 reduces the level of CTNNBIP1 in the nucleus, and therefore increasing the interaction between β-catenin and TCF/LEF, leading to the upregulation of the Wnt/β-catenin signaling pathway in thyroid cancer and promoting thyroid cancer cell proliferation, invasion, and migration." (PMID 34162394, 2021).
cancer (17 papers, 2015 to 2025). A tumor composed of atypical neoplastic, often pleomorphic cells that invade other tissues. "Its overexpression could induce changes in gene expression causing adipogenic differentiation and cancer development probably by downregulating catenin beta interacting protein 1 CTNNBIP1, which modulates Wnt cell signaling." (PMID 38668382, 2024). "Lastly, CTNNBIP1, a β-catenin interacting protein, is involved in the regulation of Wnt signaling, a pathway frequently dysregulated in cancer." (PMID 40151638, 2025). "In this regard, adipogenic differentiation and cancer development have been suggested by downregulation of catenin beta interacting protein 1 CTNNBIP1 modulating Wnt cell signaling." (PMID 38668382, 2024). "Our findings suggest that CTNNBIP1 is a suppressor of cancer migration, thus making it a potential prognostic predictor for OS." (PMID 35075228, 2022). "Previous researches showed that CTNNBIP1 negatively regulates cancer progression." (PMID 30424816, 2018). "Therefore, strategies that increase the CTNNBIP1 expression may be useful as methods of cancer prevention and treatment." (PMID 31766223, 2019). "To further investigate the function of CTNNBIP1-CLSTN1, and support its basic role of principle cell maintenance, we transfected siRNAs targeting the chimera in multiple human non-cancer cell lines, HEK-293T, HUVEC and LO2 cell lines." (PMID 37503100, 2023). "The results we present here provide further evidence that CTNNBIP1-CLSTN1 is commonly expressed in various cell types and is expressed at similar levels in normal cells and cancer cells." (PMID 37805599, 2023). "The results we presented here provide further evidences that CTNNBIP1-CLSTN1 is commonly expressed in miscellaneous cell types, and to a similar level in normal and cancer cells." (PMID 37503100, 2023). "CTNNBIP1 and TUBA1A were considered as proto-oncogenes in some of the cancers and the short transcript of two genes was related to the poor survival of the LUAD patients." (PMID 35954243, 2022). "In summary, CTNNBIP1-CLSTN1 is ubiquitously expressed in normal and cancer cells." (PMID 37503100, 2023). "In our previous study on E2F1-driven transactivation of downstream targets and its function in cancer cells, we have shown that inhibitor of β-catenin and TCF4 (ICAT), also known as the β-catenin interacting protein 1 (CTNNBIP1), is a direct transcriptional target of E2F1." (PMID 32326181, 2020). "In addition, the CTNNBIP1-CLSTN1 expression level in noncancerous cell lines was not evidently different from that in cancer cell lines." (PMID 37805599, 2023).
tumor (14 papers, 2013 to 2024). "Our results exhibited that METTL3 overexpression repressed tumor growth, elevated m6A level and circDLC1 expression, reduced miR-671-5p expression, and enhanced CTNNBIP1 expression." (PMID 35474040, 2022). "Concerning the potential target genes of this miRNA, only the expression of CTNNBIP1 was significantly upregulated in both, primary (p = 0.001) and liver metastatic (p = 0.0098) tumor tissue of CRC patients compared to adjacent colon tissue." (PMID 33255928, 2020). "On average, the tumor samples demonstrated lower levels of CTNNBIP1 expression than that of the normal samples (p < 0.001)." (PMID 31766223, 2019). "We also examined the mRNA level of CTNNBIP1 in tumor tissue and adjacent normal tissue and compared it with that of miR-215." (PMID 26317904, 2015). "However, we found that CTNNBIP1 mRNA expression was down-regulated as the stage increased, indicating its role in tumor progression." (PMID 33123276, 2020). "Moreover, CTNNBIP1 was significantly upregulated in primary tumor tissue and metastatic liver tissue of CRC patients compared to adjacent colon tissue." (PMID 33255928, 2020). "Therefore, CTNNBIP1 would seem to possibly function as a tumor suppressor by inhibiting Wnt/β-catenin signaling, and thus blocking the oncogenic phenotype." (PMID 31766223, 2019). "To test whether CTNNBIP1 exerts a protective role in survival outcome, we carried out a univariate (CTNNBIP1 expression, sex, smoking habit, and tumor stage status) and a multivariate Cox regression analysis on this cohort." (PMID 31766223, 2019). "Importantly, we observed that the CTNNBIP1 is decreased in the tumor tissue compared to adjacent normal tissue." (PMID 26317904, 2015). "Through TCGA database and qRT-PCR analysis, we showed that CTNNBIP1 level was significantly downregulated in PTC tissues, suggesting a potential anti-tumor role." (PMID 30424816, 2018). "We also examined the expression of TGF-β1, β-catenin phosphorylation, CTNNBIP1, α-SMA, and fibronectin in tumor tissue and adjacent normal tissue by Western blot." (PMID 26317904, 2015).
CTNNBIP1 also shares sentences with these, for which no sentence is quoted: colon cancer (3 papers); lentivirus infection (2); ovarian cancer (2); acute myeloid leukemia (1); acute promyelocytic leukemia (1); anencephaly (1); atherosclerosis (1); cervical cancer (1); clear cell carcinoma (1); dermatosparaxis (1); diabetes (1); dilated cardiomyopathy (1); Down syndrome (1); gastric adenocarcinoma (1); infection (1); laminopathies (1); leukemia (1); mastitis (1); metabolic disease (1); neuroblastoma (1); ovarian serous carcinoma (1); pulmonary fibrosis (1); renal carcinoma (1); Stillbirth (1); Werner syndrome (1).